RRM2 (ribonucleotide reductase regulatory subunit M2)
Diseases named in the same sentence as RRM2 in open-access papers (continued):
Sharing a sentence is not in itself a finding about the gene and the disease.
colorectal cancer (43 papers, 2013 to 2025). A primary or metastatic malignant neoplasm that affects the colon or rectum. "As an oncomiR, miR-211 suppresses the expression of RRM2 to enhance metastasis and recurrence in patients with colorectal cancer who harbor a K-RAS gene mutation." (PMID 33536579, 2021). "RRM2B intriguingly exerts opposite activity to RRM2 and its expression associates with a better survival of colorectal cancer patients." (PMID 27733154, 2016). "RRM2 was found to be associated with poor prognosis in lung and colorectal cancer." (PMID 34986845, 2022). "RRM2 is associated with poor prognosis in lung and colorectal cancer." (PMID 34986845, 2022). "Previous studies have demonstrated that MYBL2 directly transcriptionally regulates RRM2 expression in colorectal cancer cell lines." (PMID 40885709, 2025). "It has been observed that RRM2 overexpression in gastric, bladder, and colorectal cancers dramatically enhances cellular invasiveness, angiogenesis, and metastasis." (PMID 33380233, 2021). "CCNA2, MAD2L1, DLGAP5, and RRM2 were all significantly related to the pathological stages of colorectal cancer and were also closely related to the stage of lymph node metastasis." (PMID 33519906, 2020). "In this study, we found that the cAMP responsive element binding protein 1 (CREB1) acted as a transcription factor of RRM2 gene in human colorectal cancer (CRC)." (PMID 27801665, 2016). "Prognostic significance of low RRM2 transcript level for poor colorectal cancer patient’s outcome observed by the present study contradicts the previously published data." (PMID 27733154, 2016). "High RRM2 level was poor survival predictor in colorectal cancer patients reflecting the established in vitro ability of RRM2 to enhance cellular invasiveness and genetic instability." (PMID 27733154, 2016). "The role of RRM2 in malignancy has been demonstrated in several solid cancers including bladder, pancreatic, gastric and colorectal cancers, and has been attributed to increased proliferation and invasion." (PMID 25213022, 2014). "Interestingly, a study has indicated that MYBL2 directly binds to the RRM2 promoter and promoted its transcription in colorectal cancer cells." (PMID 40885709, 2025). "ERCC1, RRM1, RRM2, and hENT-1 have been proposed as potential predictive biomarkers of treatment response in several types of tumors, including lung, pancreatic, ovarian, and colorectal cancer." (PMID 34353292, 2021). "Suppression of RRM2 inhibited cell growth and invasion in colorectal cancer." (PMID 33858512, 2021). "In this study, through searching in cancer-omics databases and immunohistochemistry validation with clinical samples, we showed that the expression of MYBL2, a key oncogenic transcriptional factor, was significantly upregulated correlatively with RRM2 in colorectal cancer (CRC)." (PMID 34234118, 2021). "RRM2 is overexpressed in numerous cancers including nasopharyngeal, ovarian and colorectal cancers." (PMID 33858512, 2021). "RRM2 has also been reported to be a prognostic biomarker in colorectal cancers." (PMID 24637958, 2014).
colorectal cancer (continued). "Knockdown of RRM2 through specific small interfering RNA (siRNA) displayed effective antitumor activity in various solid tumors, like head and neck cancer, including oral squamous cell carcinoma, ovarian cancer, gastric adenocarcinoma, hepatocellular carcinoma, and colorectal cancers." (PMID 31119182, 2019). "Transcription factor E2F1 could promote RRM2 expression in colorectal cancer cell lines." (PMID 29651323, 2018). "Three highly expressed, colorectal cancer-biased chimeric RNAs, RRM2-C2orf48, METTL21B-TSFM, and SF3A2-AMH, were validated by RT-PCR and Sanger sequencing." (PMID 41155268, 2025). "Among them, we found that CCNA2, MAD2L1, DLGAP5, and AURKA were related to the overall survival (OS) of colorectal tumors, while RRM2 and AURKA had the relation between disease-free survival (DFS) and colorectal cancer." (PMID 33519906, 2020). "There are no previous data on CREB1 in CD, but it has been related to other diseases like human colorectal cancer, where CREB1 acts as a TF for tumor driver RRM2, or glioblastoma, where CREB1 acts as a mediator of the induction of TGFβ2." (PMID 29748492, 2018). "Low RRM2 transcript and UPB1 methylation levels present separate poor prognosis factors for colorectal carcinoma patients and should be further investigated." (PMID 27733154, 2016).
cervical cancer (35 papers, 2010 to 2025). A primary or metastatic malignant neoplasm involving the cervix. "These analyses suggest that KDM6A, KDM6B, and RRM2 help cervical cancer cells tolerate HPV E7-associated replication stress independently of TLS gene expression, highlighting the substantial investment that cells commit to mitigating this stress." (PMID 36266721, 2022). "The ribonucleotide reductase subunit M2 (RRM2) was found to be significantly upregulated in cervical cancer tissue and is linked to promoting the progression of cervical cancer." (PMID 34790674, 2021). "Combining the subnetwork with the result of module trait association analysis, the possible mechanisms for RRM2 to promote the progression of cervical cancer formed as follows." (PMID 32922202, 2020). "RRM2 is likely to become a novel potential diagnostic and prognostic biomarker of cervical cancer." (PMID 34790674, 2021). "RRM2 is likely to become a novel potential diagnostic and prognostic biomarker of cervical cancer and provide evidence to support the study of mechanisms for cervical cancer." (PMID 32922202, 2020). "In addition, there are some genes and proteins that have been associated with the effects and mechanisms of RRM2 in cervical cancer progression." (PMID 32922202, 2020). "Moreover, we associated the expression of RRM2 with clinicopathological variables of patients with cervical cancer, and investigated the relationship of its expression with cancer recurrence and patient survival." (PMID 24637958, 2014). "In addition, the relationship between RRM2 and other biomarkers may provide more evidence for the underlying mechanisms of cervical cancer progression." (PMID 32922202, 2020). "The current investigation elucidated that CEBPD serves as an upstream regulatory factor for key genes, including MYC, IL6, JUN, RRM2, and VEGFA, all of which have been linked to an unfavorable prognosis in cervical cancer patients." (PMID 38926832, 2024). "There was evidence that the lncRNA LINC00958 enhanced radioresistance via miR-5095/RRM2 in cervical cancer." (PMID 35600868, 2022). "This study aims to investigate the potential molecular mechanism of RRM2 for promoting the development of cervical cancer based on The Cancer Genome Atlas (TCGA) and the Gene Expression Omnibus (GEO)." (PMID 32922202, 2020). "RRM2 was significantly upregulated in cervical cancer tissues when compared to normal tissues in TCGA, GSE63514, GSE7410, GSE7803 and GSE9750 (P<0.05)." (PMID 32922202, 2020). "In conclusion, the expression of RRM2 is upregulated in cervical cancer and promotes cancerous progression." (PMID 32922202, 2020). "Our previous study had indicated that RRM2 plays a critical role in the diagnosis and treatment of cervical cancer." (PMID 32922202, 2020). "In terms of patients' characteristics, similar results were obtained with the expression of RRM2 significantly higher in cervical cancer patients than healthy people with respect to age, tumor grade, ethnic group, stages, histological type and weight (P<0.05)." (PMID 32922202, 2020). "Based on current outstanding research, we paid special attention and interest to the potential mechanism of RRM2 in cervical cancer." (PMID 32922202, 2020). "RRM2 was then correlated with the clinicopathological variables of cervical cancer and patient survival." (PMID 24637958, 2014). "The staining of RRM2 was nuclear and the expression pattern of RRM2 protein in tumor tissues was in tumor cores in cervical cancer tissue microarrays." (PMID 24637958, 2014). "The expression levels of RRM2 protein of SiHa cervical cancers were 2.3–3.6 folds more than those of Caski cervical cancers." (PMID 24637958, 2014). "The correlation of ribonucleotide reductase M2 (RRM2) immunoreactivity in 103 cancer tissue cores with clinicopathological variables in the cervical cancer patients." (PMID 24637958, 2014).
cervical cancer (continued). "When the RRM2 gene was knocked down in the SiHa cervical cancer cells using shRRM2 #354 and RRM2 #962, the level of RRM2 protein was reduced more significantly in the SiHa shRRM2 #354 than in the #962 cell lines." (PMID 24637958, 2014). "The RRM2 expression was significantly different among the cervical cancer, high-grade dysplasia, low-grade dysplasia and normal tissues (p<0.001, Kruskal-Wallis H method)." (PMID 24637958, 2014). "When the H scores of RRM2 in the cervical cancer tissues were a median value of 1 or more, their immunohistochemical expressions were regarded as being high (positive); otherwise, they were regarded as being low (negative)." (PMID 24637958, 2014). "The impact of RRM2 on cell viability was investigated in SiHa cervical cancer cells after RRM2 knockdown and the addition of cisplatin, which induces inter- and intra-strand DNA crosslinks." (PMID 24637958, 2014). "In cervical cancer, the upregulation of RRM2 could promote cervical carcinogenesis via ROS-ERK1/2-HIF-1α-VEGF-induced angiogenesis." (PMID 36678539, 2022). "Another study found that human papillomavirus E7 oncoprotein increased the expression of RRM2 to promote angiogenesis in cervical cancer and that inhibiting RRM2 activity may be a new therapeutic strategy for human cervical cancer." (PMID 36153508, 2022). "In the present study, we investigated the promotion role of RRM2 for cervical cancer using WGCNA." (PMID 32922202, 2020). "MiR-140-3p by targeting RRM2 could impede the proliferation of human cervical cancer cells to induce cell-cycle arrest and early apoptosis." (PMID 33330110, 2020). "However, the mechanisms showing how RRM2 exerted its active role in the progression of cervical cancer were still unclear." (PMID 32922202, 2020). "At present, the study of mechanisms for RRM2 in cervical cancer is limited." (PMID 32922202, 2020). "Therefore, for the main purpose of revealing the potential molecular mechanism of RRM2 for promoting the development of cervical cancer, we carried out our investigation based on The Cancer Genome Atlas (TCGA) and Gene Expression Omnibus (GEO)." (PMID 32922202, 2020). "RRM2 may exert its promoted role in cervical cancer by reducing the number of stromal cells, increasing the number of tumor cells and promoting lymphocyte infiltration." (PMID 32922202, 2020). "The results of the present study found that RRM2 may exert its promoted effect in cervical cancer by reducing the number of stromal cells, increasing the number of tumor cells and promoting lymphocyte infiltration." (PMID 32922202, 2020). "However, relatively little is known about the role of RRM2 in cervical cancer and even less is known of the mechanisms responsible for its effects." (PMID 32922202, 2020). "Our results suggest that RRM2 could be a new molecular marker for the diagnosis and clinical outcomes of cervical cancer." (PMID 24637958, 2014). "RRM2 is a new molecular marker for the diagnosis and clinical outcomes of cervical cancer." (PMID 24637958, 2014). "To date, few studies have investigated the implication of RRM2 in cervical cancer." (PMID 24637958, 2014). "Therefore, the objectives of this study were to investigate the clinical implication of RRM2 in cervical cancer." (PMID 24637958, 2014). "We detected whether cancer cell viability was reduced after the addition of cisplatin using MTT assay if the RRM2 gene was knocked down in cervical cancer cells." (PMID 24637958, 2014). "This implies that cervical cancer cells with elevated RRM2 expression have better cell viability." (PMID 24637958, 2014). "By screening the hub nodes from the co-expression network, results suggested that RRM2 may co-express with relevant genes to regulate the number of stromal/tumor cells and the process of lymphocyte infiltration to promote the progression of cervical cancer." (PMID 32922202, 2020).
cervical cancer (continued). "Interestingly, we found that RRM2 may exert its promoted role in cervical cancer by reducing the number of stromal cells, increasing the number of tumor cells and promoting lymphocyte infiltration." (PMID 32922202, 2020). "However, the mechanisms showing how RRM2 promote cervical cancer are still unclear." (PMID 32922202, 2020). "Furthermore, our secondary objective was to determine whether RRM2 could be used as a biomarker for the prognosis of cervical cancer." (PMID 32922202, 2020). "Therefore, if the RRM2 gene is knocked down in SiHa cervical cancer cells, cell proliferation may be affected." (PMID 24637958, 2014). "If RRM2 could affect cancer cells proliferation, we further examined RRM2 immunoreactivity in normal, low-grade and high-grade dysplasia tissues and invasive cancer tissue specimens of the uterine cervix and defined the correlation of RRM2 expression with cervical cancer carcinogenesis." (PMID 24637958, 2014). "Studies have shown that RRM2, TK1, and TYMS in cervical cancer tissues are significantly different from healthy tissues and are significantly correlated with overall survival in cervical cancer." (PMID 35082972, 2022). "In cervical cancer, lncRNA LINC00958 regulates RRM2 by competing for miR‐5095, thereby regulating radiotherapy resistance." (PMID 32934196, 2020). "Cervical cancer cell lines were examined for the basal expression of hENT1, dCK, RRM1, RRM2, CDA genes and then their sensitivity to gemcitabine was evaluated." (PMID 22427797, 2012). "The outcomes of this assessment substantiated our preliminary observations, revealing the upregulation of RRM2 and VEGFA, alongside the downregulation of RFC4, EXO1, PCNA, TOP2A, and TYMS in cervical cancer tissues relative to normal cervical epithelial tissues." (PMID 38926832, 2024). "For instance, patients with cervical cancer with positive RRM2 expression showed a higher recurrent rate and lower survival rate than those with negative RRM2 expression." (PMID 33411689, 2020). "This also implies that the cervical cancer patients whose cancer tissues exhibited a negative RRM2 expression had a better prognosis, and therefore the number of these patients who received cisplatin-containing therapy was very limited." (PMID 24637958, 2014).
hepatocellular carcinoma (35 papers, 2016 to 2025). A malignant tumor that arises from hepatocytes. "DENV infection prompted colocalization and interaction between RRM2 and furin in hepatoma cells and liver tissues of infected mice, with enhancement of RRM2 expression and furin stability." (PMID 41341853, 2025). "Celastrol inhibits hepatocellular carcinoma cell proliferation by inducing ferroptosis, with RRM2 playing a key role in modulating its effects on tumor growth and ferroptosis." (PMID 39315094, 2024). "Conversely, when NTP/dNTP ratio is low in the hepatoma cell lines (e.g., Huh7, expression of RRM2 is elevated), HCV would suppress the expression of RRMs to increase the cellular NTP/dNTP ratio to support HCV replication." (PMID 39339888, 2024). "Suppression of RRM2 expression not only hinders HBx-induced autophagy, but also worsens the cellular G1/S blockage and reduces the HBx-induced malignant growth of hepatocellular carcinoma tumors, while stimulating apoptosis." (PMID 39256879, 2024). "The aim of this study was to assess the importance of RRM2 in hepatocellular carcinoma (HCC) based on the Cancer Genome Atlas (TCGA) database." (PMID 37056349, 2023). "Through the bioinformatics analysis, we found that RRM2 expression was increased in hepatocellular carcinoma compared with normal liver tissues, indicating a potential function for RRM2 in tumorigenesis." (PMID 37056349, 2023). "Upregulation of RRM2 mRNA and protein levels was also confirmed in hepatoma cells infected with the HCV strain JFH1." (PMID 36768940, 2023). "Among others, RRM2 has been reported as a member of the ferric iron-binding ferritin superfamily and that RRM2 engaged in the iron metabolism in hepatocellular carcinoma." (PMID 37434783, 2023). "RRM2 inhibitor osalmid inhibited proliferation and migration, promoted cell apoptosis, triggered cell cycle arrest, and induced DNA damage of hepatocellular carcinoma cells." (PMID 35928445, 2022). "It was reported that RRM2 overexpression was observed in various types of cancer, and that patients with liver cirrhosis and hepatocellular carcinoma exhibited high levels of RRM2." (PMID 27855657, 2016). "Interestingly, inhibiting RRM2 in hepatocellular carcinoma cells using celastrol has been shown to induce ferroptosis and suppress cell proliferation, migration, and invasion." (PMID 40630134, 2025). "The expression of RRM2 in hepatocellular carcinoma and normal tissues was analyzed, and the difference in RRM2 expression levels was confirmed (P <0.001); RRM2 expression was higher in LIHC (Liver Hepatocellular Carcinoma) tissues than in normal tissues (P <0.001)." (PMID 37056349, 2023). "However, the clinical significance of RRM2 in hepatocellular carcinoma has been less studied." (PMID 37056349, 2023). "Ribonucleotide reductase 2 (RRM2), a subunit of ribonucleotide reductase (RRM), plays an anti-ferroptotic role in hepatocellular carcinoma cells." (PMID 40959280, 2025). "Increased RRM2 mRNA and protein expression levels were detected in HCV-infected hepatocytes from chimeric mice and hepatoma cells infected with the HCV strain JFH1." (PMID 39339888, 2024). "It showed that increased RRM2 mRNA and protein expression levels were detected in HCV-infected hepatocytes from chimeric mice and also in hepatoma cells infected with the HCV strain JFH1." (PMID 37513740, 2023). "For both serotypes, the intracellular viral RNA copy number was substantially higher in RRM2 siRNA-transfected hepatoma cells compared to those that were non-transfected or transfected with control siRNA." (PMID 41341853, 2025). "Moreover, knockdown of RRM2 inhibited HBV replication and RRM2 inhibitors (e.g., Pterostilbene) suppressed HBV replication and hepatocellular carcinoma proliferation." (PMID 37513740, 2023).
hepatocellular carcinoma (continued). "Also, the expression of YBX1 mRNA significantly positively correlated with RRM2, TK1, and TYMS mRNA expression in 374 human hepatocellular carcinoma samples (TCGA)." (PMID 32587247, 2020). "High expression of RRM2 reflects enhanced DNA replication and was correlated with poor prognosis of non-CNS cancers: hepatocellular carcinoma, breast and prostate cancer." (PMID 29242629, 2017).